CHD9 (chromodomain helicase DNA binding protein 9)
Description:
Probable ATP-dependent chromatin-remodeling factor. Acts as a transcriptional coactivator for PPARA and possibly other nuclear receptors. Has DNA-dependent ATPase activity and binds to A/T-rich DNA. Associates with A/T-rich regulatory regions in promoters of genes that participate in the differentiation of progenitors during osteogenesis (By similarity).
Synonyms: CReMM; CHD-9; KIAA0308; KISH2; PRIC320; FLJ12178; BC022889; AD013
Tractability: PROTAC: UniProt records ubiquitination sites on it; ubiquitination databases record sites on it.
Target class: Enzyme; Hydrolase
Gene: Protein-coding gene on chromosome 16 (53,054,991 to 53,329,150, forward strand). Ensembl gene ENSG00000177200.
Subcellular location: Cytoplasm; Nucleus
Subcellular location (Human Protein Atlas): Nucleoplasm; Cytosol
Pathways (Reactome):
Circadian clock: BMAL1:CLOCK,NPAS2 activates circadian expression; Expression of BMAL (ARNTL), CLOCK, and NPAS2; RORA,B,C and NR1D1 (REV-ERBA) regulate gene expression
Metabolism: Activation of gene expression by SREBF (SREBP); PPARA activates gene expression; Regulation of lipid metabolism by PPARalpha
Cellular responses to stimuli: Cytoprotection by HMOX1; Heme signaling
Chromatin organization: CHD6, CHD7, CHD8, CHD9 subfamily
Developmental Biology: Transcriptional regulation of white adipocyte differentiation
Organelle biogenesis and maintenance: Transcriptional activation of mitochondrial biogenesis
Gene Ontology:
Molecular function: ATP hydrolysis activity; ATP binding
Cellular component: cytoplasm; cytosol; nucleoplasm; nucleus
Genetic constraint (gnomAD): Loss-of-function variants: 52 observed, 212.31 expected, observed/expected ratio (o/e) 0.24, 90% interval 0.19 to 0.31. The upper end of that interval is the gene's LOEUF score, 0.31, which puts it in group 1 of 6, group 1 being the genes least tolerant of losing a copy. Missense variants: 2,266 observed, 2,894 expected, observed/expected ratio (o/e) 0.78, 90% interval 0.75 to 0.81. Synonymous variants: 936 observed, 999.08 expected, observed/expected ratio (o/e) 0.94, 90% interval 0.89 to 0.99.
Homologues: Orthologues: chimpanzee CHD9 (99% identical), macaque CHD9 (99% identical), dog CHD9 (97% identical), pig CHD9 (96% identical), guinea pig CHD9 (92% identical), mouse Chd9 (91% identical), rat Chd9 (90% identical), tropical clawed frog chd9 (75% identical), zebrafish chd9 (58% identical). Paralogues in human: CHD7 (50% identical), CHD8 (44% identical), CHD6 (41% identical), CHD5 (16% identical), CHD4 (15% identical), CHD3 (15% identical), CHD2 (14% identical), CHD1 (14% identical), EP400 (12% identical), SRCAP (12% identical), SMARCA4 (12% identical), SMARCA2 (11% identical), and 18 more.
Diseases named in the same sentence as CHD9 in open-access papers:
CHD9 is named in the same sentence as 29 diseases in open-access papers, as found by Europe PMC text mining. Sharing a sentence is not in itself a finding about the gene and the disease. The quoted sentences say what the papers report.
breast carcinoma (4 papers, 2017 to 2025). "CHD3 and CHD9 are the most deleted CHD genes in breast cancer, with 60% and 55% of breast cancer patients showing heterozygous loss, respectively." (PMID 41278204, 2025). "Non-functional studies:CHD9 showed heterozygous loss in approximately 55% of breast cancer." (PMID 41278204, 2025).
gastric cancer (2 papers, 2020). A primary or metastatic malignant neoplasm involving the stomach. "We demonstrated that circPDZD8 not only up-regulated the expression of CHD9 by sponging miR-197-5p but also promoted the progression of gastric cancer cells via modulating CHD9 in vitro." (PMID 33049714, 2020). "What’s more, there was a negatively correlation between the expression of miR-197-5p and CHD9 in gastric cancer tissues (R2=-0.6, P < 0.001)." (PMID 33049714, 2020). "Overall, we revealed that interference with circPDZD8 inhibited the progression of gastric cancer via modulating CHD9 by competitively binding miR-197-5p." (PMID 33049714, 2020). "Collectively, these results revealed that circPDZD8 modulated the expression of CHD9 by serving as a ceRNA for miR-197-5p in gastric cancer cells." (PMID 33049714, 2020). "Then we analyzed the expression of CHD9 in gastric cancer tissues and found that CHD9 expression was strikingly upregulated in gastric cancer tissues compared to normal tissues." (PMID 33049714, 2020). "CircPDZD8 knockdown repressed the progression of gastric cancer cells by sponging miR-197-5p and down-regulating CHD9." (PMID 33049714, 2020). "The study mainly researched the influence of circPDZD8 on the progression of gastric cancer by modulating miR-197-5p/CHD9 axis, hoping to find novel markers for the diagnosis of gastric cancer." (PMID 33049714, 2020). "Similarly, CHD9 expression in gastric cancer cells was inversely regulated by miR-197-5p and a distinct negative correlation between them was found in gastric cancer tissues." (PMID 33049714, 2020). "In this part, we aimed to explore whether circPDZD8 could regulate CHD9 expression through miR-197-5p in gastric cancer cells." (PMID 33049714, 2020). "In our study, CHD9 was enormously promoted in gastric cancer." (PMID 33049714, 2020). "Importantly, circPDZD8 could up-regulate CHD9 expression by sponging miR-197-5p, and modulate cell progression by regulation of the miR-197-5p/CHD9 axis in gastric cancer." (PMID 33049714, 2020). "What’s more, up-regulation of CHD9 partially regained the suppressive impacts of miR-197-5p-mimics on proliferation and migration of gastric cancer cells, which was consistent with the previous results that the overexpression of CHD9 could promote the process of gastric cancer cells." (PMID 33049714, 2020). "However, whether CHD9 could be modulated by circRNA and miRNA has never been reported in gastric cancer." (PMID 33049714, 2020).
glioblastoma (2 papers, 2016 to 2020). The most malignant astrocytic tumor (WHO grade IV). "Analysis of a panel of human cancer cell lines revealed high CHD9 protein levels in SNB19 glioblastoma and K562 chronic myelogenous leukemia cell lines." (PMID 32453735, 2020). "In silico analysis shows that CHD7 and CHD9 are well expressed in brain tumor, and CHD7 is expressed highly in Glioblastoma multiforme (GBM) compared to normal brain." (PMID 27955690, 2016).
neuroblastoma (2 papers, 2016 to 2017). Neuroblastoma (NB) is the most common solid, extracranial childhood tumor. "Together, these data suggest that CHD9 mutations are relevant for neuroblastoma progression." (PMID 27009842, 2016). "Mutations in CHD9 emerged as relatively recurrent in neuroblastoma (4%)." (PMID 27009842, 2016). "In this scenario, loss of CHD9 would lead to progression of neuroblastoma." (PMID 27009842, 2016). "Indeed, the osteogenesis inhibition favours bone invasion by neuroblastoma cells and here we show that the downregulation of CHD9 is correlated with metastasization and low survival rates." (PMID 27009842, 2016). "We speculate that CHD9 inactivation may increase metastatic spread to the bone, which is the second most common site of metastasis in neuroblastoma." (PMID 27009842, 2016). "Furthermore, an analysis encompassing 491 cancer types identified ALK and CHD9 as highly expressed in neuroblastoma." (PMID 27009842, 2016). "Interestingly, several sequence alterations in other genes involved in chromatin regulation in neuroblastoma have been found, including EP300, CREBBP, TTF2, KDM5A, CHD9, and gene IKZF1, which might undergo somatic mutations and promote NB occurrence." (PMID 28055978, 2017). "So far, CHD9 mutations have not been reported in previous Next Generation Sequencing studies probably because in our study we used a restricted and homogeneous sub-set of aggressive neuroblastoma and because we profiled most of the tumors by DT-seq reaching coverage higher than 700x." (PMID 27009842, 2016).
brain tumor (1 paper, 2016). "In silico analysis in the present showed the higher expression of CHD7 and CHD9 in brain tumor." (PMID 27955690, 2016).
colorectal cancer (1 paper, 2024). A primary or metastatic malignant neoplasm that affects the colon or rectum. "The function of chd9 in human cancer is controversial, and it is considered to be an oncogene in renal cell carcinoma or a tumor suppressor gene in colorectal cancer (CRC)." (PMID 39452097, 2024).
lymphoma (1 paper, 2020). A malignant (clonal) proliferation of B- lymphocytes or T- lymphocytes which involves the lymph nodes, bone marrow and/or extranodal sites. "In order to assess whether CHD9 showed an effect on lymphoma gene expression, we profiled lymphomas from EμMyc Chd9 wildtype, heterozygous and knockout mice by RNA-seq." (PMID 32453735, 2020). "Moreover, downregulation of CHD9 expression is reported in multiple myeloma and diffuse large B–cell (DLBCL) lymphoma patients." (PMID 32453735, 2020). "Moreover, although several murine and human studies suggested a role for Chd9 in solid tumors and lymphomas, CHD9 depletion did neither accelerate nor impair EμMyc-driven lymphomagenesis." (PMID 32453735, 2020).
malignant peripheral nerve sheath tumor (1 paper, 2016). Malignant peripheral nerve sheath tumor (MPNST) is a rare and often aggressive soft tissue sarcoma occurring in a wide range of anatomical sites. "Indeed, clusters of insertional events of CHD9 driving cancer progression have been reported in diverse tumors including malignant peripheral nerve sheath tumors in which CHD9 is deleted in 6.7% of cases." (PMID 27009842, 2016).
melanoma (1 paper, 2016). A malignant, usually aggressive tumor composed of atypical, neoplastic melanocytes. "Among genes mutated in at least two of those three melanomas, we identified TSC2 (tuberous sclerosis 2), CHD9 (chromodomain-helicase-DNA-binding protein 9) and NALCN (sodium leak channel, non-selective)." (PMID 27095580, 2016).
Stroke (1 paper, 2016). Sudden impairment of blood flow to a part of the brain due to occlusion or rupture of an artery to the brain. "Observational studies have suggested that cholesterol lowering with statins may not be effective in primary prevention of stroke for low risk patients without preexisting CHD9, a finding that is in contrast to the results of other trials." (PMID 28979904, 2016).
tendinopathy (1 paper, 2023). "Additionally, CHD9 has been implicated in upregulating RUNX2 which may shed light on tendinopathy-associated ectopic ossification." (PMID 37821884, 2023).
thyroid (1 paper, 2019). "Chd9 and Dmbt1, among the others, are part of several complexes/gene networks regulating cell cycle/apoptosis in the endoderm and might be involved in thyroid carcinogenesis, a role not proposed until now." (PMID 30621213, 2019).
cancer (8 papers, 2016 to 2024). A tumor composed of atypical neoplastic, often pleomorphic cells that invade other tissues. "The authors proposed further that loss of CHD9, chromatin related mesenchymal modulator, leads to NB tumor progression as seen in other cancer types." (PMID 29259192, 2017). "The same study demonstrated that acute depletion of CHD9 in human cancer cells elicited more robust gene expression changes, suggesting that CHD9 is a highly context-dependent chromatin regulator." (PMID 34828433, 2021). "Publicly available data sets indicate that CHD9 is overexpressed in cancers of neuronal and hematopoietic origin." (PMID 32453735, 2020). "Lastly, we explored gene expression regulation by CHD9 in human cancer cell lines." (PMID 32453735, 2020). "To address the role of CHD9 in gene expression regulation in these human cancer cell lines, we generated SNB19 and K562 cell lines bearing doxycycline-inducible short hairpin RNAs (shRNA) targeting CHD9 and confirmed successful depletion of the protein upon knockdown induction by Western blotting." (PMID 32453735, 2020). "Germline deletion of Chd9 only moderately affects gene expression in tissues and derived cells, whereas acute depletion in human cancer cells elicits more robust changes suggesting that CHD9 is a highly context-dependent chromatin regulator that, surprisingly, is dispensable for mouse development." (PMID 32453735, 2020). "Chd9, for instance, might promote cancer development, inducing the transcription of genes involved in the assembly of ribosome and of gene controlling invasiveness." (PMID 30621213, 2019). "CHD9, a cancer driver gene, was the most significantly altered (4.0% of cases) after ALK." (PMID 27009842, 2016). "It is intriguing that chromatin modeler CHD9 is the most promising cancer driver." (PMID 27009842, 2016). "Moreover, mouse insertional mutagenesis experiments support CHD9 as a cancer driver gene (Candidate Cancer Gene Database)." (PMID 27009842, 2016). "Further, it has been demonstrated that Chd9−/− (knockout) mice are viable and develop normally, given the incidence of CHD9 dysregulation in many cancers this finding supports a vital role in the DNA damage response." (PMID 33435571, 2021).
tumor (5 papers, 2017 to 2020). "What’s more, the expression levels of circPDZD8, miR-197-5p and CHD9 in isolated tumor tissues were examined." (PMID 33049714, 2020). "Here, we describe the first Chd9 knockout mice and study its contribution to development and lymphomagenesis, a tumor subtype in which insertional mutagenesis experiments suggested a potential role of CHD9." (PMID 32453735, 2020). "Further study, such as examining the effect of CHD 9 expression on cellular function by knocking out or expressing CHD 9 genes in CRC cell lines, will be done to explore the tumor suppressor mechanism of CHD9." (PMID 30043858, 2018). "And more importantly, knockdown of circPDZD8 could impede the tumor growth via the miR-197-5p/CHD9 axis in vivo." (PMID 33049714, 2020). "We speculated that CHD9 might be a putative tumor suppressor gene, and could inhibit the development of CRC by participating in DNA repair processes." (PMID 30043858, 2018). "To more rigorously document a potential role of CHD9 in lymphomagenesis, we crossed the Chd9–/–strain with EμMyc transgenic mice hypothesizing that if CHD9 would have an oncogenic or tumor-suppressing activity this should be revealed through an acceleration or delay of tumorigenesis, respectively." (PMID 32453735, 2020).
infection (1 paper, 2024). The state of being infected such as from the introduction of a foreign agent such as serum, vaccine, antigenic substance or organism. "After infection with C. irritans, the expression of fru-miR-204a in the gill of T. rubripes was down-regulated, while the expression of chd9 was up-regulated." (PMID 39452097, 2024).
CHD9 also shares sentences with these, for which no sentence is quoted: autism spectrum disorder (2 papers); acute coronary syndrome (1); bipolar disorder (1); chronic myelogenous leukemia (1); endometriosis (1); glioma (1); heart failure (1); Insulin resistance (1); multiple myeloma (1); neurodegenerative disease (1); Obesity (1); osteosarcoma (1); renal cell carcinoma (1); schizophrenia (1).